STAT1 (signal transducer and activator of transcription 1)
Diseases named in the same sentence as STAT1 in open-access papers (continued):
Sharing a sentence is not in itself a finding about the gene and the disease.
glioma (continued). "The results reveal that the expression levels of STAT1 signaling pathway downstream response genes in glioma tissues were lower than those in matched adjacent noncancerous tissues and further decreased with advanced clinical grade and in the tumors with poor pathologic differentiation." (PMID 34784299, 2021). "Moreover, patients bearing STAT1-intermediate glioma have longer disease-specific survival when compared with STAT1-high glioma (p = 0.0023), and shorter disease-specific survival when compared with STAT-low glioma (p = 0.0279)." (PMID 27705947, 2016). "Previous finding has shown the interaction between NMI and STAT1, yet none was reported in glioma." (PMID 25669971, 2015). "To conclude, the collective evidence indicates that TME of IDH‐mutant glioma is less infiltrated with immune cells due to IDH‐induced downregulation of chemokines, which in the case of STAT1, was shown not to be related to methylation." (PMID 38339779, 2024). "Western blot analyses demonstrated that, whereas STAT2 and STAT4 showed no prominent or consistent changes in expression, STAT1, STAT3 and STAT5 expression were increased in glioma tissues compared with neighboring non-tumor tissue." (PMID 31530290, 2019). "Although NMI has been shown to interact with STAT1, a member of JAK/STAT pathway, none of that was reported in glioma." (PMID 25669971, 2015). "The relationship between B2M and seven inflammatory activity related signatures was then explored in pan-gliomas and LGG, B2M expression had positive correlation with HCK, LCK, MHC-I, MHC-II, STAT1 and interferon metagenes, and negative correlation with IgG metagene expression." (PMID 33658560, 2021).
hepatocellular carcinoma (80 papers, 2010 to 2026). A malignant tumor that arises from hepatocytes. "IFI6 was one of a number of ISGs shown to inhibit yellow fever virus (YFV) infection in STAT1-deficient human (STAT1−/−) fibroblasts or in human hepatoma cells." (PMID 25757571, 2015). "Aberrant STAT1 signaling is observed in human hepatocellular carcinoma (HCC) and has been associated with the modulation of cell proliferation and survival." (PMID 26617467, 2015). "Zhu demonstrated that SNPs in the STAT1 gene (homozygotes of the minor alleles at SNP rs867637, rs3771300, or rs2280235) are associated with a risk of developing hepatocellular carcinoma in Chinese people." (PMID 21625390, 2011). "In the context of mouse tumor models, NR4A1 (Nuclear Receptor 4A1) has emerged as a significant player, mediating NK-cell dysfunction in hepatocellular carcinoma through the IFNγ/p-STAT1/IRF1 pathway." (PMID 39920136, 2025). "As for the STAT1, it has previously been reported to be a tumor suppressor in hepatocellular carcinoma and in esophageal squamous cell carcinoma." (PMID 40226609, 2025). "Nr4a1 was noted to mediate NK cell dysfunction in hepatocellular carcinoma via the IFN-γ/p-STAT1/IRF1 pathway." (PMID 40083382, 2025). "For example, RIG-I acts as a tumor inhibitor via enhancing STAT1 activation in hepatocellular carcinoma and acute myeloid leukemia." (PMID 39055888, 2024). "Clinical sample analysis indicates a correlation among HKDC1 expression, STAT1 phosphorylation, and survival in patients with hepatocellular carcinoma treated with atezolizumab (anti-PD-L1)." (PMID 38351096, 2024). "SM suppresses hepatocellular carcinoma growth by reducing STAT1-mediated MTCH1 expression, thereby inducing apoptosis and ferroptosis." (PMID 39315094, 2024). "MiR-155-5p modulates STAT1 expression suppressing SOCS1 expression in hepatoma cells and, thus, promoting the JAK/STAT signaling." (PMID 38098120, 2023). "This qualifies STAT1 as a novel marker for evaluating the prognosis of patients with hepatocellular carcinoma." (PMID 35646925, 2022). "Carboxypeptidase X M14 family member 2 overexpression promotes proliferation and migration, predicts an unfavorable prognosis of osteosarcoma, and accelerates progression through the regulation of the gp130/JAK2/Stat1 pathway in hepatocellular carcinoma." (PMID 35686102, 2022). "Helicobacter hepaticus co-infected with Hepatitis B virus recruited innate lymphoid cells and promoted hepatocellular carcinoma (HCC) tumorigenesis through an IFN-γ/p-STAT1 axis." (PMID 34532297, 2021). "Very recent work demonstrates an important role for NAD+ in STAT1 activation and PD-L1 induction by IFNγ in hepatocellular carcinoma cells." (PMID 34726598, 2021). "From these, it was demonstrated that atorvastatin impedes STAT1 activation, thereby reducing the expression of PD-L1 in both transcription and translation levels in hepatocellular carcinoma cells." (PMID 34445462, 2021). "In this study, we confirmed that TNFα significantly augments the PD-L1-inductive effect of IFNγ in HepG2 cells, a human hepatocellular carcinoma cell line, and this effect was through activation of STAT1, JNK, and NFкB pathways." (PMID 34445462, 2021). "In such a way, that STAT1 lost its ability to block cell cycle progression and hinder hepatoma cell transformation in a course of prolonged inflammatory injury." (PMID 32878239, 2020). "We establish, based on quantitative measurements obtained for the hepatoma cell line Huh7.5, an ordinary differential equation model for IFNα signal transduction that comprises the feedback regulators STAT1, STAT2, IRF9, USP18, SOCS1, SOCS3, and IRF2." (PMID 32696599, 2020). "Given their importance in the innate antiviral response and the connection between HCV and hepatocellular carcinoma, we examined the expression of several key mediators of the host antiviral response, STAT1, STAT2, and NF-κB." (PMID 31374104, 2019).
hepatocellular carcinoma (continued). "To this end, we compared the expression of twelve genes either linked to the induction of innate immunity (STAT1, STAT2, PKR) or IFN effector genes (OAS1/2, IFIT1–3, RSAD2, MX1, TRIM14, ISG15) in HCV-infected hepatoma cells and mature iHLCs." (PMID 29497123, 2018). "And RIG-I, serving as a tumor suppressor, augmented STAT1 activation in hepatocellular carcinoma through its CARDs competitively binding to STAT1 against the negative regulator SHP1." (PMID 30250402, 2018). "In this study, using the CRISPR/Cas9 system, we show that IFN-α can inhibit HCV replication independently of STAT1 in Huh-7.5 human hepatoma cells." (PMID 27929099, 2016). "IL-1β can also attenuate interferon-induced antiviral activity and STAT1 activation in the liver, and modulate immune responses in hepatitis virus-related hepatocellular carcinoma." (PMID 23704929, 2013). "In this report, we have investigated regulation of the MAPK and STAT1 signaling pathways by IFN α in human hepatoma cells." (PMID 21466707, 2011). "Changes in mitogen-activated protein kinase (MAPK) and STAT1 pathways were evaluated in human hepatoma cells Huh7 and HepG2 upon IFN alpha treatment." (PMID 21466707, 2011). "In conclusion, our results demonstrate that IFN α up-regulates MAPK and STAT1 signaling pathways in human hepatoma cells, and provide useful information for understanding the IFN signaling events." (PMID 21466707, 2011). "For example, upon treatment of hepatoma cells and primary human macrophages with IL-6-type cytokines (e.g. IL-6 or OncostatinM) STAT1 phosphorylation can be observed but most of the phosphorylated STAT1 is rather trapped in STAT1/STAT3 heterodimeric complexes." (PMID 20719000, 2010). "Importantly, RIG-I has previously been shown to enhance the IFN-α response in the absence of infection by amplifying IFN-α effector signaling via strengthening STAT1 activation in both in vitro and in vivo models of hepatocellular carcinoma." (PMID 39995872, 2025). "In addition, IFN-γ was found to trigger ferroptosis in hepatocellular carcinoma by activating the STAT1/IRF1/ACSL4 axis." (PMID 40140647, 2025). "STAT1 was significantly overexpressed in hepatocellular carcinoma." (PMID 35646925, 2022). "STAT1 is an important factor in the occurrence and development of hepatocellular carcinoma." (PMID 35646925, 2022). "This study suggests that STAT1 may be a key oncogene in hepatocellular carcinoma and provides evidence that the JAK2 inhibitor lestaurtinib is a potent antiproliferative agent that warrants further investigation as a targeted therapy for HCC." (PMID 35646925, 2022). "They found that (U-) STAT1 was significantly upregulated in HCC tumor tissues and mainly expressed in the cytoplasm while the deletion of (U-) STAT1 in hepatoma cells may block the cell cycle and limit cell growth." (PMID 35646925, 2022). "However, in STAT1 gene-silenced hepatocellular carcinoma cells, IL-27 mediated expression of γ-fibrinogen, which is typically induced by IL-6." (PMID 28255204, 2017). "Similarly, it was reported that HCVc inhibits nuclear import of STAT1 in transiently transfected HuH-7 hepatoma cells, and inhibits both STAT1 and STAT2 in human osteosarcoma-derived cell lines that express HCVc37." (PMID 27786268, 2016). "Moreover, HCV infection of immortalized human hepatocytes has been to increase the expression of total STAT1 while studies in hepatoma cell lines showed that Core binds STAT1 directly to prevent phosphorylation." (PMID 24788809, 2014). "In contrast, ribavirin may even reduce phosphorylation of various signalling molecules including STAT1 in human hepatoma cells." (PMID 24751903, 2014). "Thus, the aim of this study is to reveal regulation of MAPK and STAT1 signaling pathways by IFN α in human hepatoma cells Huh7 and HepG2." (PMID 21466707, 2011).
hepatocellular carcinoma (continued). "IFN alpha up-regulates MAPK and STAT1 pathways in human hepatoma cells, and may provide useful information for understanding the IFN signaling." (PMID 21466707, 2011). "Hou and colleagues reported that RIG-I enhanced IFN-α response in hepatocellular carcinoma (HCC) via strengthening STAT1 activation, suggesting RIG-I is a tumor suppressor in HCC." (PMID 28057020, 2017). "Of note, overlapping genomic occupancy between TBX3 and β-catenin at relevant cancer-inducing genes, such as MYC, RAS, and STAT1 is also found in hepatocellular carcinoma (HCC) cells, both in cell lines (HepG2 from ENCODE) and in two independent patient-derived HCC biopsies (our data)." (PMID 40343989, 2025). "Cytokine-signaling-related proteins associated with lipid rafts include, for example, IL-2 and IL-15 receptor subunits in T cells, interferon receptors and STAT1 in macrophages, STAT1 and STAT3 in hepatoma cells." (PMID 39563446, 2024). "(2009), hepatoma cells and hepatocytes stimulated with IL-27 displayed sustained activation of STAT-1 and STAT-3, leading to an IFN-γ-like STAT-1-dependent response." (PMID 38720890, 2024). "The oxidative hepatic environment in obesity induces PTPN2 inactivation and the resultant enhanced STAT1 and STAT3 signaling, which promotes T cell recruitment and ensures non-alcoholic steatohepatitis and fibrosis, as well as hepatocellular carcinoma." (PMID 36077422, 2022). "Taken together, our study provides evidence that ASCs can be used to inhibit hepatocellular carcinoma, potentially by the IFN-β-induced JAK/STAT1 pathway." (PMID 32210710, 2020). "Human hepatoma cells and primary murine hepatocytes were treated with TNF-α/LPS/IL-6/IL-10 and USP18, phosphorylated (p)-STAT1 and myxovirus (influenza virus) resistance 1 (Mx1) expression was determined." (PMID 27009955, 2016). "In hepatocellular carcinoma(HCC), intestinal bacterial lipopolysaccharide regulates the expression of PD-L1 on the surface of cancer cells by upregulating METTL14 and METTL14-mediated m6A modification of MIR155HG, modulating the miR-223/STAT1 axis." (PMID 39372415, 2024). "Strikingly, the overexpression of the HB spliced protein (HBSP) or reverse transcriptase’-RNaseH (RT’-RH) proteins in hepatoma cells, similarly to POL, prevented the nuclear translocation of STAT1 and STAT2 and the activation of STAT1 in response to IFN-α treatment." (PMID 38675956, 2024). "Deficiency of PTPN2 in hepatocytes resulted in maladjustment of signal transduction and activation of transcription 1 (STAT1) and STAT3, which eventually accelerated the progression on the spectrum of steatosis-NASH-cirrhosis-hepatocellular carcinoma (HCC) in mice." (PMID 35269812, 2022). "In hepatocellular carcinoma, IFIT3 could bind signal transducer and activator of transcription 1 (STAT1) and STAT2 to enhance STAT1–STAT2 heterodimerization and nuclear translocation upon IFN-α treatment, thus promoting IFN-α effector signalling." (PMID 34418997, 2021). "Activation of STAT1 by miR-145-5p was only induced in biliary tract cell lines but not in hepatocellular carcinoma cell lines." (PMID 30886199, 2019). "Thus, we have demonstrated that STAT1 is predominantly present in unphosphorylated state in HCC tissues and human hepatoma cell lines." (PMID 30456450, 2019). "While in hepatocellular carcinoma and acute myeloid leukemia, RIG-I acts as a tumor suppressor through either augmenting STAT1 activation by competitively binding STAT1 against its negative regulator SHP1 or inhibiting AKT-mTOR signaling pathway by directly interacting with Src respectively." (PMID 28593618, 2018). "Since STAT1 inhibits Erk in hepatocellular carcinoma cells, ZOL-mediated downregulation of STAT1 may trigger Erk activation in 786-O cells." (PMID 23741352, 2013).
hepatocellular carcinoma (continued). "Moreover, recent reports demonstrated that IL-1β can activate the STAT1 pathway by negatively modulating ERK2 activation in the target cells and synergistically elevates PD-L1 expression through the coordination with IFNγ in hepatocellular carcinoma." (PMID 38166970, 2024). "Moreover, activation of IFNγ-STAT1 signaling is not influenced by EZH2 expression in hepatoma cells." (PMID 31727135, 2019). "Furthermore, the activation of STAT1 by miR-145-5p was specifically observed in gallbladder carcinoma and cholangiocarcinoma but not in hepatocellular carcinoma cells." (PMID 30886199, 2019). "From a molecular perspective, it is important to note that, given the dissociation between STAT-1 and STAT-3 activation pathways, obesity may contribute to the development of NASH and hepatocellular carcinoma (HCC) through different independent mechanisms." (PMID 38248843, 2024). "STAT1 was significantly positively correlated with PD1 (r = 0.448), PD-L1 (r = 0.444), CTLA-4 (r = 0.436), FGFR2 (r = 0.354), FGFR3 (r = 0.36), and IDO1 (r = 0.387) in HCC, suggesting that targeting STAT1 may improve the efficacy of immunotherapy for hepatocellular carcinoma." (PMID 35646925, 2022). "Therefore, we had to prestimulate hepatoma cells with exogenous human IFN-β (1,000 U/ml) for 24 hours, which then led to a significant induction of expression of both IFIT-1 and STAT1 and its phosphorylation (P-STAT1) in all three hepatoma cell lines (lane 2 in all panels)." (PMID 27119111, 2015). "However, when adding resminostat (5 μmol/l) on IFN-β prestimulated (1,000 U/ml) hepatoma cells, a profound suppression of IFIT-1 expression was observed in HepG2, Hep3B, and PLC/PRF/5 hepatoma cells, but no alteration in the phosphorylation status of STAT1 (lane 4 in all panels)." (PMID 27119111, 2015).
colitis (71 papers, 2013 to 2025). Inflammation of the colon. "We sought to identify the target genes of STAT1 that were upregulated in mice with DSS-induced colitis and to further investigate the mechanism underlying the contribution of STAT1 to IBD through H3K27ac." (PMID 34112215, 2021). "Studies have reported amelioration of experimental colitis has been observed in STAT1-deficient mice, suggesting has a pro-inflammatory effect." (PMID 34589089, 2021). "T-cell and macrophage depletion was associated with reduced expression of colitis-associated genes such as Il22, Ifng, Stat1 and Tnfa." (PMID 33127658, 2020). "The data demonstrate that epithelial STAT1 is required for colitis‐associated intraepithelial infiltration of CD8+ TCRαβ+ granzyme B+ T cells in male but not in female mice." (PMID 29419930, 2018). "We employed mice with specific deletion of STAT1 in intestinal epithelial cells to investigate tumor cell‐intrinsic functions in colitis‐associated CRC." (PMID 29419930, 2018). "We investigated sex‐specific STAT1 functions in colitis and colitis‐associated CRC using mice with specific STAT1 deletion in intestinal epithelial cells (STAT1∆IEC)." (PMID 29419930, 2018). "Mice with mutationsthat abrogate gp130-induced STAT1/3 signalling have an increased susceptibility toexperimentally-induced colitis." (PMID 26848037, 2016). "Looking at IL-22, it is tempting to relate those complications to constitutive IL-22 expression by intestinal NK-like/innate lymphoid cell populations and pathogenic properties of STAT1 in human colitis." (PMID 23382730, 2013). "Given the critical role of RBBP9 in directly suppressing the phosphorylation of STAT1, we examined whether the loss of STAT1 reversed the apoptotic phenotype of epithelial cells and rescued the increased susceptibility of Rbbp9-/- mice to experimental colitis." (PMID 39631567, 2025). "Furthermore, a study employing an acute colitis model revealed significant improvements in disease state among STAT1-deficient mice in comparison to wild-type mice." (PMID 38420127, 2024). "Moreover, STAT1 has been proposed as a tumor suppressor particularly in colitis‐associated CRC, in turn suggesting a carcinogenic potential of its disruption by the identified upstream variant." (PMID 35562597, 2022). "The susceptibility of STAT1 KO mice to development of IBD is consistent with the observation that human patients carrying a hypomorphic allele of STAT1 develop symptoms of colitis and that many genes associated with IBD susceptibility are related to the IFN pathway." (PMID 34378531, 2021). "Astragaloside IV alleviates DSS‐induced colitis by downregulating STAT‐1 to inhibit macrophage M1 polarization." (PMID 41256230, 2025). "The genetic inhibition of STAT1 or treatment with the JAK/STAT inhibitor reversed epithelial cell apoptosis and mitigated the enhanced susceptibility to DSS-induced colitis in Rbbp9-/- mice." (PMID 39631567, 2025). "Our results demonstrate that PPAR-γ/NF-κB/STAT1-mediated macrophage polarization is a central mechanism through which ZQG ameliorates experimental colitis, while acknowledging potential synergistic pathways warranting future investigation." (PMID 40860883, 2025). "This review indicated that IN alleviates colitis by activating AhR signaling and inhibiting STAT1/STAT3 signals and IL-10." (PMID 40756994, 2025). "Previous studies have corroborated these findings, demonstrating that inhibition of CXCL1 or STAT1 in murine models of ulcerative colitis alleviates colonic inflammation." (PMID 41406086, 2025). "The loss of RBBP9 enhanced the activation of interferon (IFN)/JAK/STAT1 signaling, resulting in susceptibility to DSS-induced colitis and AOM/DSS-induced CAC tumors by increasing epithelial cell apoptosis and immune activation." (PMID 39631567, 2025). "STAT1 in macrophages exacerbated inflammatory progression by upregulating NLRP3 expression in a mouse model of colitis." (PMID 38315275, 2024).